IL10 (interleukin 10)
Diseases named in the same sentence as IL10 in open-access papers (continued):
Sharing a sentence is not in itself a finding about the gene and the disease.
depression (continued). "Elevated IL-6 has served as a consistent biomarker of depression and IL-10 is proposed to influence depressive behavior through its ability to counterbalance pro-inflammatory cytokine expression." (PMID 23520517, 2013). "Central administration of IL-10 prevents the emergence of behavioral signs of depression in an LPS model of sickness behavior." (PMID 23382717, 2013). "Traditional cytokine-based theories of depression place great emphasis on the role of inflammatory cytokine elevations in depressive illness, though important work suggests that IL-10 itself plays a direct role in affecting depressive behavior." (PMID 23520517, 2013). "Because we found that IL-10 levels were positively correlated with depression severity, it will be important for future studies to examine gene expression levels following symptom remission." (PMID 24143878, 2013). "Recent literature describes concurrent increases in IL-6 and decreases in IL-10 in individuals suffering from major depression." (PMID 23520517, 2013). "A role for IL-10 in neuroprotection and the prevention of depression-like behavior has been suggested." (PMID 23382717, 2013). "The aim of this study was to examine serum levels of the proinflammatory cytokines interleukin 6 (IL-6) and tumor necrosis factor α (TNFα), and the anti-inflammatory cytokine IL-10, in perimenopausal women suffering from depression." (PMID 22490187, 2012). "Of notice, IL-10, one of the most important anti-inflammatory cytokines, proved to be relevant in depression." (PMID 19936104, 2009). "In further support of a role for IL-10 in depression, transgenic mice overexpressing this cytokine show a decreased depressive-like behavior in the FST in comparison with WT animals." (PMID 19936104, 2009). "The observation that IL-10KO mice show an increase in the adrenal and a decrease in the thymus relative weights offers another alternative mechanism for the action of IL-10 in depression: the modulation of the hypothalamic-pituitary-adrenal (HPA) axis." (PMID 19936104, 2009). "This constitutes an additional evidence that IL-10 can also be involved in the common biological pathways shared by pain and depression." (PMID 19936104, 2009). "Depression demonstrated positive causal associations with TRAIL (OR: 1.733, 95% CI: 1.234–2.435, P = .002), IL-10 (OR: 1.438, 95% CI: 1.012–2.043, P = .043), and smoking initiation (OR: 1.049, 95% CI: 1.004–1.095, P = .032), with no heterogeneity or horizontal pleiotropy." (PMID 41327674, 2025). "However, within that study, higher IL-10 concentrations were observed in patients with later-onset depression compared to both early-onset patients and healthy individuals." (PMID 41226404, 2025). "The inconsistency of cytokine alterations between anxiety and depression suggests that deficits of anti-inflammatory cytokines like IL4/IL-10 may be disease specific." (PMID 41462928, 2025). "Similarly, IL-10 has been found to act as an anti-inflammatory cytokine with both decreased and increased levels of IL-10 found in people with depression." (PMID 39867847, 2025). "In addition to these neurotrophic factors, some cytokines have been highlighted within the clinical picture of depression, with some being studied as potential biomarkers for this disorder, such as IL‐1β and IL‐10." (PMID 41030588, 2025). "They demonstrated that proBDNF/p75NTR signaling is upregulated in the immune cells of MDD patients, particularly in CD4+ and CD8+ T cells, and plays a role in modulating inflammatory responses; increases in IL-1β and IL-10 levels were positively correlated with major depression scores." (PMID 41465304, 2025). "Reduced IL-10 levels, commonly seen in depression, may weaken immune regulation and amplify the inflammatory burden in COPD." (PMID 40823578, 2025).
depression (continued). "Elevated cytokines such as IL-10, IL-1β, and TNF-α are linked to common comorbidities of depression, including hypertension and diabetes, and may serve as potential markers of disease severity and treatment response." (PMID 41226736, 2025). "However, a more nuanced understanding shows that other cytokines, such as interleukin-10 (IL-10) and interferon-gamma (IFN-γ), also play significant roles in the neuroinflammatory processes associated with depression." (PMID 40305200, 2025). "Fifteen studies involving measurements of inflammatory proteins and level of depression in 1102 individuals with MS were included in the meta-analysis: five for interleukin (IL)-10 (LPS and PHA), four for tumour necrosis factor (TNF)-α, four for interferon (IFN)-γ, and four for IL-6 (LPS and PHA)." (PMID 39867847, 2025). "Patients with depression often exhibit increased levels of interleukin-6 (IL-6), IL-1β, IL-10, tumour necrosis factor-α (TNF-α), CRP, and transforming growth factor-β (TGF-β), many of which are produced in response to cellular stress through inflammasome activation." (PMID 41226736, 2025). "Hamilton Depression Scale scores showed a positive correlation with IL-10 (β = 0.512, 95% CI: 0.128–0.896, p = 0.012), whereas SCOPA-AUT scores were inversely linked to IFN-γ (β = −0.588, 95% CI: −0.962 to −0.214, p = 0.003), with adjusted R2 values of 41.2 and 49.5%, respectively." (PMID 40672460, 2025). "Proinflammatory cytokines tumor necrosis factor α (TNF-α), interleukin-1 β (IL-1β), and interleukin-10 (IL-10) are elevated in major depressive disorder and HS, suggesting a possible pathophysiological process for increased inflammatory symptoms in comorbid patients." (PMID 39173146, 2024). "After treatment with interferon and ribavirin, there was positive correlation between depression severity and cytokines including IL-8, IL-10, IL-16, TNF-α, TGF-β and IFN-β in patients with chronic hepatitis C. Both pro- and anti-inflammatory responses were activated." (PMID 38459460, 2024). "Some authors proposed IL-10 as a key cytokine in depression." (PMID 38646609, 2024). "In addition, the drugs for depression treatment, such as Fluoxetine and Sertraline, have displayed anti-inflammatory properties, including IL-10 up-regulation." (PMID 38822367, 2024). "Patients with CI, even with schizophrenia and major depression, have higher circulating levels of inflammatory markers, including IL-1β, IL-2, IL-4, IL-6, IL-8, IL-10, TNF-α, soluble TNF receptor 1 (sTNFR1), sTNFR2, MCP-1, MCP-3, CRP, and high-sensitivity CRP (hsCRP)." (PMID 38739942, 2024). "In this study, we investigated the relationship between plasma cytokine levels and suicide risk stratification in adolescents with depression, and found high levels of IL-6, TNFα, IFN-γ, and IL-10 in the high-suicide-risk group, which is consistent with the results of previous studies." (PMID 39882160, 2024). "In addition, XYS reduced the levels of IL-1β, IL-6, and TNF-α and increased the level of IL-10 in the sera of the mice with depression-like behaviors." (PMID 38378622, 2024). "It has been suggested that there may be some kind of feed-forward regulation in depression, with IL-6 driving IL-10 release and thereby suppressing the inflammatory response." (PMID 39882160, 2024). "IL-10, anti-inflammatory cytokine, reverses depression-like behavior." (PMID 38459460, 2024). "Overall, we emphasized the therapeutic role of IL-10 for depression." (PMID 38822367, 2024). "IL-10 has been suggested play a role in depressive disorders." (PMID 38646609, 2024). "This is inconsistent with earlier animal and human studies which found a lack of expression of the IL-10 gene or low levels of IL-10 was associated with depression and administration of IL-10 reverses depression." (PMID 37680396, 2023). "Moreover, individuals with depression were shown to have abnormal IL-10 levels, resulting in an upset pro- and anti-inflammatory cytokine balance." (PMID 37840785, 2023).
depression (continued). "One of such studies demonstrated increased IL-6 levels in women with depression during late pregnancy and early postpartum period, whereas another study showed a decreased interferon-gamma/IL-10 ratio, which may indicate impaired cell-mediated immunity." (PMID 37840785, 2023). "Studies have shown that inflammatory factors IL-1β, IL-6, TNF-α, and CRP are elevated and anti-inflammatory factors IL-4, IL-8, and IL-10 are decreased in peripheral and cerebrospinal fluid and correlate with patients’ symptoms and disease duration in depression and anxiety." (PMID 36624089, 2023). "The median IL-10 level was 0.99 pg./mL in women with depression (min." (PMID 37840785, 2023). "The current study suggested that both TNF-α (-308G/A) and HHV-6 might affect TNF-α, IL-6, and IL-10 expression, influencing the severity and progression of depression via inflammatory processes." (PMID 37766304, 2023). "IL-10 is also a predictive marker of severe depressive disorders." (PMID 37892657, 2023). "In another study, the administration of Faecalibacterium prausnitzii via oral gavage for 4 weeks in a chronic unpredictable mild stress model in rats resulted in decreased depression-like behaviors accompanied by increased IL-10 and decreased IL-6 and CRP levels." (PMID 35546876, 2022). "By contrast, IL-10 concentration levels regularly decreased as depression progressed." (PMID 35326343, 2022). "IL-10 knockout mice showed learned helplessness in animal depression models, a symptom that could be reverted by application of IL-10, whereas IL-10 administration led to increased motor activity in wild-type mice." (PMID 36614020, 2022). "Similarly, elevated IL-10 and CRP levels are associated with PTSD and depression in chronic mTBI population." (PMID 35053845, 2022). "Depression-related symptoms were shown to be associated with low circulating IL-10 levels in women but not in men." (PMID 36313784, 2022). "Elevated IL-1β, IL-6 and lowered IL-10 in the model rats indicated there may be a low Th2 or/and M2 immune response in pain and depression comorbidities." (PMID 35733107, 2022). "Based on this research, we selected IL-10 and some other well-known pro- and anti-inflammatory cytokines in our study to investigate the relationship between the immune response and the development of depression." (PMID 34733143, 2021). "For the comparison of bipolar depression versus unipolar depression, an area under the curve (AUC) of 0.69 with 0.62 sensitivity and 0.66 specificity using three selected biomarkers (IL-4, thiobarbituric acid reactive substances, and IL-10) was achieved." (PMID 33578686, 2021). "Conversely, mice overexpressing IL-10 have reduced depression." (PMID 33717157, 2021). "IL-10, a prototypical anti-inflammatory cytokine, was closely related to depression." (PMID 32714875, 2020). "Data showed elevation of pro-inflammatory markers and depression of IL-10." (PMID 36561228, 2020). "In major depression, significant associations were established between increased plasma KOR/MOR levels, on the one hand, and elevated plasma IL-6 and IL-10, on the other, indicating that immune - EOS interactions play a role in the pathophysiology of depression." (PMID 32858974, 2020). "However, this latter study reported that depressive symptoms during pregnancy, as well as the IL6 and IL-10 biomarkers, were significant predictors of postpartum Edinburgh Perinatal Depression Scale (EPDS) score." (PMID 30943938, 2019). "Likewise, there is reason to believe that low levels of the anti-inflammatory cytokine interleukin-10 (IL-10) accompany high levels of depression." (PMID 29684053, 2018). "Results of a decreased IL-4-responsiveness of microglia as well as the inhibition of IL-10-signaling leading to depression-like behavior in animal models of depression demonstrate the need for further investigations on the role of anti-inflammatory agents in depression." (PMID 30524320, 2018).
depression (continued). "IL-10 levels in patients with early-onset depression (<20 years of age) were reported to have no obvious differences with those in healthy controls, but were reported to be elevated in patients with late-onset depression (≥ 20 years of age)." (PMID 29856741, 2018). "IL-10 was also found to be a critical factor as intranasal administration of a neutralizing antibody to IL-10 to target the meninges prolonged lipopolysaccharide-induced depression-like behavior in wild type mice." (PMID 30102966, 2018). "In addition, results for circulating anti-inflammatory interleukin (IL)-10 are mixed, although findings in chronic heart failure, renal disease, and also animal research clearly suggest a link between reduced IL-10 and depression." (PMID 29218020, 2017). "Although this is the first study to examine the effect of hip fracture and depression on IL10 production by CD4+ T cells, a few studies examining the effect of chronic stress such as caregiving and academic stress have reported increased IL10 production and secretion." (PMID 26112234, 2016). "However, when considering the TNF-α to IL-10 ratio, a measure of the ratio of pro- to anti-inflammatory loading, maternal immune effects on offspring depression differed significantly by sex (χ2=13.9, degrees of freedom=4, P=0.008)." (PMID 27244231, 2016). "Among females, higher maternal TNF-α:IL-10 was associated with reduced odds of depression (OR=0.51; CI=0.32, 0.81), whereas, among males, high maternal TNF-α:IL-10 was associated with elevated odds of depression (OR=1.86; CI=1.02, 3.39)." (PMID 27244231, 2016). "Thus, our results propose potential of IL-4 and IL-10 to dampen elevated vulnerability to stress-related events to achieve more comprehensive treatment of depression." (PMID 26521132, 2015). "Thus, our results suggest that the reduced IL-4 and IL-10 levels in serum with hippocampal M2 markers may be involved in the stress vulnerability after imipramine discontinuation, and the restoration and modulation of these factors may be useful to some forms of depression-associated conditions." (PMID 26521132, 2015). "Additionally, IL-4 and IL-10 are suggested to play a significant role in affecting depression-like behaviors." (PMID 26521132, 2015). "Depression severity was related to increased IL-10, P2RY1, P2RX1, and TRPV4 expression." (PMID 24143878, 2013). "Recent clinical work reports on elevated IL-6 and decreased IL-10 in depression." (PMID 23520517, 2013). "Serum samples from 65 perimenopausal women, 41 with depression and 24 without depression, were assessed for serum IL-6, TNFα and IL-10 by conventional enzyme-linked immunosorbent assays." (PMID 22490187, 2012). "In the hypothesis outlined here we proposed IL-10 as an important link between the changes in hormonal and cytokine milieus that are of recognized relevance for depression." (PMID 19936104, 2009). "In addition to the increased helplessness in mice that lack the expression of IL-10, other studies also reported that modulation of IL-10 impacts on psychophysiological alterations frequently observed in depression." (PMID 19936104, 2009). "Of relevance for this hypothesis is the observation, in depressed patients and also in animal models of depression, of increased IL-10 levels after treatment with several classes of antidepressants." (PMID 19936104, 2009). "Haplotype analysis of SNPs from the IL10 gene cluster with major depressive disorder." (PMID 19087313, 2008). "However, cytokines like IL-10 and interferon gamma yield inconsistent patterns across studies, suggesting that inflammation in depression may vary significantly between subtypes or individuals." (PMID 40428308, 2025). "IL-10, another key anti-inflammatory cytokine, suppresses the production of pro-inflammatory mediators such as TNF-α and IL-1β, while enhancing tissue regeneration and immune homeostasis.In depression-related studies, elevated IL-4 levels have been associated with better emotional stability." (PMID 40453075, 2025).
depression (continued). "Therefore, further understanding of the role of IL-10 in depression suicide is required." (PMID 39882160, 2024). "Additionally, including other pro- and anti-inflammatory markers beyond TNF-α and IL-10 could provide a more comprehensive understanding of the inflammatory processes in depression." (PMID 37680396, 2023). "Interestingly, plasma IL-10 was increased in PTSD patients with comorbid depression." (PMID 37629192, 2023). "Thus, possible associations between depression subtypes and its pathogenic characteristics with controls may be drawn through plasma levels of C-reactive protein (CRP), IL-6, IL-10, and leukocyte subpopulation in blood composition." (PMID 36217471, 2022). "Furthermore, in mice, administration of IL-10 reduced the depression-like behaviors." (PMID 36339940, 2022). "Similarly, chronically elevated IL-10 and CRP levels could help identify mTBI patients at risk of developing depression and PTSD." (PMID 35053845, 2022). "As an anti-inflammatory factor, the concentration of IL-10 exhibited an opposite trend; it was significantly lower in the model group than in the sham group (p < 0.01), while gallic acid and P2X7shRNA significantly increased serum IL-10 levels in visceral pain and depression rats (p < 0.01)." (PMID 35682841, 2022). "After eliminating the reason that multicollinearity (tolerance, 0.694 to 0.871; variance inflation factors, 1.148–1.441) among all identified variables would lead to deviation in the results, we speculated that IL-10 possibly played a significant role in depression in patients with glioma." (PMID 35757220, 2022). "While IL-10 is studied less frequently than IL-6, others illustrate that IL-10 concentrations are also increased in patients with depression, compared to healthy controls and similar to IL-6, they may be confounded by underlying inflammation and/or stress disorders." (PMID 34765010, 2021). "IL-10 assessment might be more sensitive to changes in depression severity." (PMID 33447872, 2021). "Furthermore, previous studies have shown that ketamine could alleviate LPS-induced depression-like behaviors, which were related to increased expressions of IL-1β and IL-6 and decreased expression of IL-10 in the rats." (PMID 32522211, 2020). "Taken together, IL-10 may have beneficial actions both within cognition and depression." (PMID 32828124, 2020). "Interestingly, the present data showed that FGF2 not only ameliorated the increased production of pro-inflammatory cytokines in the neuroinflammation induced model of depression, but also enhanced the level of IL-10, a representative anti-inflammatory cytokine." (PMID 30135647, 2018). "Thus, we propose that IL-4 and IL-10 may be able to lower the vulnerability to some forms of stress- and depression-related conditions after imipramine discontinuation." (PMID 26521132, 2015). "Thus, we next analyzed the expression levels of the genes encoding for three of the most relevant pro-inflammatory cytokines, IFN-γ, IL-1β, and TNF, for the anti-inflammatory cytokine IL-10 and for the enzyme iNOS, all previously addressed in studies on the etiology of depression." (PMID 26696854, 2015). "The combined role of IL-6 and IL-10 in depression have garnered recent attention with the recognition of human populations suffering from major depression displaying commensurate increases in IL-6 and decreases in IL-10, providing direct biological correlation with this animal model." (PMID 23520517, 2013). "However, the levels of IL-10 in the blood and sigmoid colon mucosa in the anxiety-depression IBS-D group (27.36±8.24 and 24.31±5.66, respectively) were significantly lower than those in the non-anxiety-depression IBS-D group (30.34±7.33 and 28.45±3.34, respectively; P<0.05)." (PMID 23935726, 2013). "For analyses related to IL-10 (PHA and LPS), type of depression measure was found to be a significant moderator." (PMID 39867847, 2025).